NF1 (neurofibromin 1)
Diseases named in the same sentence as NF1 in open-access papers (continued):
Sharing a sentence is not in itself a finding about the gene and the disease.
tumor (continued). "Indeed, a considerable number of studies have identified somatic copy number alterations (CNA) and concomitant gene expression changes in benign and malignant NF1-associated tumours." (PMID 25884485, 2015). "Recurrent mutations are found in GBM tumor in NF1 RAS-GAP domain." (PMID 26496030, 2015). "Furthermore, tumor genome analyses of diverse cancers have identified NF1 mutations in sporadic but lethal cancers arising in adults, such as malignant brain tumors, ovarian cancers, and lung cancers." (PMID 26000738, 2015). "The most common NF1-associated tumor is the benign peripheral nerve sheath tumor or neurofibroma." (PMID 26666878, 2015). "The utility of these drugs in NF1-deficient tumours may be worth investigating, especially in combination with Ras or AURKA inhibitors, which may have synergistic effects." (PMID 25026295, 2014). "Loss of heterozygosity (LOH) was observed in 1/1 SDHB, 11/11 VHL and 3/3 NF1-associated tumours." (PMID 24466223, 2014). "The methylation profile of the TAGLN gene may be another biomarker that is useful for decision making with regard to the tumor progression of NF1-associated tumors." (PMID 25109740, 2014). "Loss-of-function mutations in the NF1 gene can also lead to the development of a wide range of abnormalities in the cardiovascular, musculoskeletal and nervous systems, in addition to the predisposition to benign and malignant tumours." (PMID 25026295, 2014). "NF 1 is caused by loss of function mutations in the tumor-suppressor NF1 gene." (PMID 24899893, 2014). "There is also an unmet need to develop novel systemic therapies for treating NF1-deficient tumours." (PMID 25026295, 2014). "Inactivation of Nf1 caused an increase in Ras activity in murine or some human tumor cells." (PMID 25301738, 2014). "Furthermore, mutations and genomic alterations of NF1 have been reported in a number of other cancer cells and tumor tissues." (PMID 23335975, 2013). "Intriguingly, IGFBP1 also seems to correlate with internal tumor burden, and thus may indicate increased risk for malignant transformation in patients with NF1." (PMID 23618374, 2013). "As proof that the retained genes include genuine drivers, we note that the list of genes recurrently lost in both human and fish MPNSTs includes four tumor suppressors, NF1, NF2, SMARCB1 and PTEN, that are strongly associated with the development of human Schwann cell tumors." (PMID 24009526, 2013). "However, only after a sciatic nerve injury did loss of Nf1 expression induce tumorigenesis, providing evidence that microenvironment signals at the wound site can be tumor-promoting." (PMID 24349213, 2013). "Observations of subclonal NF1 deletions reinforced evidence from the mutation data that important driver mutations may be acquired late in the evolutionary history of the tumour." (PMID 23780408, 2013). "Potentially, the loss of one or several of the genes located within the NF1 microdeletion region in addition to the deletion of the NF1 gene, may influence tumour biology or progression." (PMID 23101500, 2012). "Under the assumption of an ordered categorical distribution, we estimated that it would have been necessary to analyze approximately 300 NF1 patients to detect a significant association between tumour volume and the T-allele with a power of 80% using the Mann–Whitney–Wilcoxon test (α=5%)." (PMID 23101500, 2012). "The two-hit tumor suppressor hypothesis for NF1 predicts that all cells carry a constitutional mutation and a particular cell acquires a second mutation to initiate tumor formation." (PMID 22550514, 2012). "Mutations in rat sarcoma viral oncogene homolog (RAS) or its pathway-associated genes may also cause tumor initiation in sporadic MPNSTs that lack NF1 mutations." (PMID 23319880, 2012). "The newly discovered functions of NF1 might be of clinical relevance for understanding the invasiveness and tumor progression of NF1-associated tumors and for drug development." (PMID 22776759, 2012).
tumor (continued). "The large and complex NF1 gene is located on chromosome 17 and mutations of that gene resulting with hyperplasias, hamartomas and benign and malignant neoplasms occur in a variety of tissues and organs as a result of abnormal tumor suppression." (PMID 23049566, 2012). "Mutations of the NF1 gene which is located on chromosome 17 lead to abnormal tumor suppression." (PMID 23049566, 2012). "The loss of one SUZ12 allele in patients with germline NF1 microdeletions may well influence ANRIL-mediated expression regulation of the CDKN2A/CDKN2B tumour suppressor genes." (PMID 23101500, 2012). "Our research into the second, that is somatic, NF1 mutation in the GISTs of both probands carrying the NF1 germline mutations started with the hypothesis that the second somatic hit would appear to be an independent event in each NF1-associated tumor." (PMID 21838856, 2011). "The NF1 gene encodes a protein named neurofibromin which has a role in tumour suppression." (PMID 20438631, 2010). "A number of studies have compared survival insporadic and NF1-associated tumours but noconsensus has been reached on whether NF1 is an independent poor prognosticfactor or not." (PMID 19360115, 2009). "Nearly half of these tumours arise in the context ofthe inherited predisposition syndrome, neurofibromatosis type 1 (NF1),suggesting that inactivation of the NF1 tumour suppressor gene might be causally related to the development of thesecancers." (PMID 18769552, 2008). "This suggests that the well-known Knudson's two-hit hypothesis may be operational, and that somatic loss of the second allele of the putative tumor suppressor function of the NF-1 gene causes development of this particular somatic malignancy." (PMID 15363097, 2004). "Imaging (MRI/CT) demonstrated an intradural-intramedullary tumor extending through the intervertebral foramen, causing severe spinal cord compression and multiplanar instability (C1-C6).The patient was diagnosed with NF-1, severe cervical kyphosis, and an intraspinal tumor." (PMID 41788354, 2026). "Indeed, NF1-deficient cells can directly promote tumor angiogenesis, as previously reported." (PMID 40877908, 2025). "Therefore, there is a clear need to discover new drugs to target NF1‐deficient tumor cells." (PMID 39129390, 2025). "Additionally, multivariate analysis identified multi-protein signatures associated with chemotherapy response in both tumor and stromal regions: high expression of NF1 in the tumor region and ERα in the stromal region were significantly linked to chemotherapy response." (PMID 40867511, 2025). "Therefore, we speculate that aberrant RAS activity in NF1‐deficient cells results in the initiation of autophagy, and that inhibition of this pathway has anti‐tumor effects." (PMID 39129390, 2025). "Indeed, our data suggest that the NF1 intact microenvironment cells may be more sensitive to MEK inhibition than NF1−/− tumor cells at least in part due to how NF1 loss modulates Ras pathway activation and feedback regulation." (PMID 40587782, 2025). "It inhibits tumor growth by regulating the activity of Ras guanosine triphosphatase, preventing GTPase activation, and regulating cell proliferation and differentiation.The study found that women with NF1 who are 50 years or older have a lower risk of BC compared to the general population." (PMID 39390525, 2024). "Therefore, NF1 mutations may contribute to a tumor-promoting immune microenvironment in the mesenchymal subtype." (PMID 38666025, 2024). "However, it must be noted that how tumor genotype contributes to the molecular phenotype-related plasticity remains unclear, i.e., NF1 mutation in human GBM is associated with a mesenchymal feature, but this has not been verified in animal models." (PMID 38273014, 2024).
tumor (continued). "In order to examine the effect of αAMR therapy on tumor growth via angiogenesis, we used MeWo cells since their own proliferation is not directly inhibited by AM blockade in vitro, which might be due to the loss of NF1 activity by these cells." (PMID 36497391, 2022). "In addition, we confirmed the prevalence of CNV alterations in ARGs in COAD patients, and CNVs seem associated with higher expression of ARGs in tumor tissues, such as NF1, COL4A2, C1GALT1, SPHK1, RUNX1, implying a potential regulatory role of CNVs on the expression of ARGs." (PMID 36505481, 2022). "In addition to NF-1 associated optic nerve gliomas in which visual stimulation could drive tumor initiation, olfactory sensory experience could also promote gliomagenesis." (PMID 36357661, 2022). "However, loss of one allele may lead to haplo-insufficiency that may be problematic for tumor suppressor genes such as NF1, a potential cause of dysregulated hematopoiesis." (PMID 35764638, 2022). "This method could also be useful in analysing somatic mutations in tumours involving the NF1 gene." (PMID 34449562, 2021). "Genomic aberrations in neurofibromin 1 (NF1) gene have been reported as one of the major characteristics of the mesenchymal GBM, and NF1 deficiency has been shown to recruit TAMs to the tumor site, indicating that reconstituting functional NF1 may prevent mesenchymal transformation in GBM." (PMID 33762019, 2021). "These cases could be explained by the presence of mosaic NF1 pathogenic variation, epigenetic alterations affecting NF1’s expression or the effect of its protein, as well as the association of this tumor type with other genetic diseases, or random, unfortunate association of sporadic OPG." (PMID 34325699, 2021). "Identification of mutations and genotype–phenotype correlation in NF1 may better explain the tumorigenesis; physical variabilities in tumor type, density, and size; differences in growth speed of the proliferative process; or the co-occurrence of other phenotypes in CNFs." (PMID 34566848, 2021). "Moreover, NF1 mouse models are heavily reliant on the Cre-Lox system, which does not accurately reflect the molecular mechanism of spontaneous loss of heterozygosity that accompanies human tumor development." (PMID 33669386, 2021). "Therefore, the role of NF1 loss for microenvironment and tumour formation may well be adapted to the central nervous system-derived malignant glial tumours, the GBM, although the literature is sparse." (PMID 35008787, 2021). "Of the remaining 21 tumours, three harboured biallelic somatic NF1 alterations; two had homozygous NF1 copy number loss (detected by visual inspection of read counts using the Integrative Genomics Viewer); three had non‐synonymous NF1 mutations; and two had a heterozygous loss of NF1." (PMID 32666581, 2020). "It is not entirely clear why the morphology is variable in tumors with NF1 mutations but several factors may contribute, including the presence of other genetic alterations, the sequence in which the mutations occur in the tumor and possibly, the cell of origin." (PMID 31258848, 2019). "Indeed, we observed that, particularly in the case of the MEK inhibitor trametinib, knockdown of NF1 in cell lines either wildtype for or with het-loss of this gene resulted in a shift in the sensitivity phenotype toward that of the tumor cells with complete ablation." (PMID 29854299, 2018).
tumor (continued). "There is often wide variation of cNF tumor size and concentration on patients' bodies, suggesting that either tumor growth is under the influence of unidentified stochastic modifiers or not all somatic mutations (the second hit mutation) leading to biallelic loss of NF1 are equivalent." (PMID 29987131, 2018). "Indeed, the interval between loss of the Nf1 tumor suppressor and tumorigenesis, and increased inflammation, may create a window of opportunity for interfering with tumor formation." (PMID 28256556, 2017). "Thus, patients with an NF1 microdeletion and a high internal tumour load couldrepresent an ultra-high risk group for MPNST." (PMID 28213670, 2017). "As such, NF1 is considered a classic tumor suppressor gene and its mechanism in NF1 is felt to be consistent with Knudson's two-hit hypothesis in which a patient carries a mutated germline NF1 gene copy and tumor development, including CN, then requires a second hit." (PMID 28099461, 2017). "Though immunotherapy is a potentially attractive therapeutic strategy, as it may facilitate the reinstatement of the immune system to its original function and empower it to explicitly recognize and target tumor cells, it has been largely unexplored for NF1-associated tumors." (PMID 29137242, 2017). "However, recognizing tumors that have inactivation of the NF1 tumor suppressor function is challenging because the loss may occur via mechanisms that do not involve mutation of the genomic locus." (PMID 28166733, 2017). "For example, germline splice site mutations in NF1 may increase the risk of tumor development." (PMID 28099461, 2017). "In our assessment of immunologic marker gene expression in NF1-associated samples, differences observed between tumor-associated Schwann cells and their respective tumors can be accounted for by the presence and contribution of stromal and other cells within the tumor microenvironment." (PMID 29137242, 2017). "In addition to the deletion of SUZ12 and ATAD5, hemizygosity forthe genes COPRS, UTP6 and RNF135 may alsocontribute to the increased tumour risk associated with NF1 microdeletions." (PMID 28213670, 2017). "Mutations of the NF1 gene, which encodes neurofibromin and is located at chromosome 17q11.2, a negative regulator of the ras signal transduction pathway that has a role in both tumor suppression and regulation of cell growth and proliferation, are responsible for the NF1." (PMID 27927206, 2016). "Additionally, NF1 mutation status could be predicted by contrast enhancing volume (AUC = 0.68, p = 0.023) and tumor bulk volume (AUC = 0.67, p = 0.032)." (PMID 26337765, 2015). "If the tumor is large enough, hypothalamic dysfunction occurs, and according to some recent data, optic pathway glioma might have stronger causative role for precocious puberty than the presence of NF1 condition." (PMID 26666878, 2015). "Finally, CALM are “tumor-like” in that they follow the Knudsen two-hit hypothesis: melanocytes in these lesions acquire a second somatic mutation in NF1." (PMID 25329635, 2014). "Thereby, they may have an increased tumor risk with a biallelic haploinsufficiency of NF1 gene." (PMID 23304574, 2012). "Hence, it was suggested that NF1 deficiency may disrupt some vascular fields, producing anatomical regions that are prone to develop tumours and malformations." (PMID 20687928, 2010). "Moreover, NF1 deficient cells express elevated levels of tumor supporting growth factors." (PMID 20686603, 2010). "This case highlights the broad tumor spectrum in NF1 and underscores the importance of comprehensive imaging, multidisciplinary management, and genetic testing for optimal outcomes." (PMID 41756333, 2026).
tumor (continued). "Studies in Nf1‐mutant optic pathway glioma mouse models demonstrate that visual circuit activity modulates tumor growth by integrating immune responses." (PMID 41583906, 2026). "NF1 acts as a tumor suppressor by accelerating RAS GTP hydrolysis, a process facilitated by SPRED1, which recruits NF1 to the plasma membrane." (PMID 41514664, 2026). "This case highlights the unique tumor biology of NF1 and emphasizes the importance of meticulous anatomic evaluation and coordinated multidisciplinary surgical planning to determine the optimal extent and approach to resection." (PMID 42238721, 2026). "Given the patient’s confirmed diagnosis of NF1, the tumor is classified as a malignant peripheral nerve sheath tumor with rhabdomyoblastic differentiation—specifically, a malignant Triton tumor (MTT)." (PMID 40630199, 2025). "Lastly, a study utilising bisulphite-modified genomic sequencing examined the methylation pattern of the NF1 promoter region in tissue samples obtained from NF1-specific tumours and peripheral blood lymphocytes from NF1 patients and healthy controls." (PMID 40843672, 2025). "About 30–40% of cases are the result of an underlying autosomal dominant familial disorder such as VHL (mutations in the VHL tumor suppressor gene), MEN2 (mutations in the RET proto-oncogene), and NF1 (mutations in the NF1 gene)." (PMID 40649858, 2025). "To address this possibility, we leveraged single-cell RNA sequencing to identify Nf1-OPG tumor-specific genes." (PMID 41497446, 2025). "Similar to tovorafenib, increased pERK levels were observed at lower concentrations and decreased pERK at higher concentrations with each type II RAF inhibitors in all three NF1-LOF tumor cell lines at the 1-hour timepoint." (PMID 40111124, 2025). "The cNFs represent an interesting case of tumor biology, since they are a highly penetrant yet benign consequence of germline NF1 haploinsufficiency." (PMID 40394150, 2025). "The NF1 gene encodes neurofibromin, a tumor suppressor protein that regulates the MAPK signaling pathway; its inactivation results in NF1, a multisystem disorder with pigmentary and tumor manifestations." (PMID 41300842, 2025). "Tumor size and quality of margins as well as NF1 have in some previous studies been shown to significantly affect OS." (PMID 41272396, 2025). "We collected 15 cNFs from four NF1 individuals and used mass spectrometry to compare the tumor tissue with the skin overlying each tumor." (PMID 40394150, 2025). "Vemurafenib served as a type I BRAF inhibitor control and as expected, pERK levels increased with vemurafenib concentration in all NF1-LOF tumor cell lines." (PMID 40111124, 2025). "First, NF‐1 treatment can selectively and effectively disrupt tumor cell GA, resulting in a significant enhancement of immunotherapeutic efficacy in vitro and in vivo experiments." (PMID 39908165, 2025). "Although cNFs and pNFs both arise from biallelic NF1 loss and have near-identical histology, they differ markedly in NF1-related signaling pathways, tumor behavior, and malignant potential." (PMID 41374990, 2025). "After targeting tumor cell GA, the morphology of NF‐1 is changed from micelles to nano‐fibers under the action of furin, thus inducing cell apoptosis as well as GA dysfunction." (PMID 39908165, 2025). "Leveraging the cell-type specific marker genes from our NF1 single-cell tumor reference dataset (MPNST vs PN enrichment score > 25), we identified 127 MPNST gene markers whose encoded protein was also assayed on the PEA antibody panel." (PMID 40585258, 2025). "While more than half of the tumours exhibited some degree of methylation, this pattern was attributed to the heterozygous background characteristic of NF1 tumours." (PMID 40843672, 2025).